TNF (tumor necrosis factor)
Diseases named in the same sentence as TNF in open-access papers (continued):
Sharing a sentence is not in itself a finding about the gene and the disease.
acute respiratory distress syndrome (continued). "Severe COVID-19 and COPD involve cytokine storms (IL-6, TNF-α) and alveolar macrophage dysfunction, leading to acute respiratory distress syndrome (ARDS) and pulmonary fibrosis." (PMID 40565232, 2025). "Cytokines, such as interleukin-6 (IL-6), interleukin-1 (IL-1), interleukin-17 (IL-17), and tumor necrosis factor-alpha (TNF-α) play a significant role in lung damage in acute respiratory distress syndrome patients through impairment of respiratory epithelium." (PMID 40429912, 2025). "The major cause of death from COVID-19 is acute respiratory distress syndrome (ARDS), which develops as a result of an accelerated inflammatory response that releases proinflammatory cytokines including interleukin (IL) and tumor necrosis factor alpha." (PMID 38390960, 2024). "It has been confirmed to alleviate lung injury of acute respiratory distress syndrome by down-regulating the mRNA expression of inflammatory factors such as TNF-α, IL-6, and IL-1β, as well as by reducing neutrophil infiltration." (PMID 37547679, 2023). "We can observe the elevating IL-6, TNF and IFNƳ serum levels in patients with severe COVID pneumonia, especially complicated by acute respiratory distress syndrome ARDS." (PMID 37608339, 2023). "IL-6 and TNF-α play a crucial role in viral-mediated respiratory disorders such as acute respiratory distress syndrome (ARDS) and acute lung injury." (PMID 35328462, 2022). "In acute respiratory distress syndrome, NETs aggravate alveolar macrophage pyroptosis, and ASC foci, caspase-1, IL-1β, IL-6, and TNF-α are significantly associated with elevated NETs." (PMID 36430491, 2022). "Immune activation and CRS were evidenced by a rapid increase in serum cytokines (IL-6, TNFα, IL-8, IL-10), acute respiratory insufficiency, and progressive acute respiratory distress syndrome." (PMID 35692034, 2022). "Studies using neutralizing antibodies to IL-17 or TNF-α in mice and in several clinical trials for acute respiratory distress syndrome (ARDS) demonstrated a positive response." (PMID 35171047, 2022). "In the exudative phase of acute lung injury/acute respiratory distress syndrome, lung M1 polarized macrophages increase, which can release TNF-α, interleukin 1 (IL-1), nitric oxide, and reactive oxygen species, thus inducing a severe inflammatory response." (PMID 35586251, 2022). "TNF, IL-1, IL-6, and IL-8 have been shown to be elevated in individuals with acute respiratory distress syndrome and septic shock." (PMID 35450105, 2022). "Levels of inflammatory cytokines and chemokines (IL-1, IL-6 and TNF-α) increase to a delayed peak at this stage while lymphocyte levels are low and inflammatory dysregulation develops into acute respiratory distress syndrome (ARDS)." (PMID 34858409, 2021). "In CRS, infusion of cytotoxic T-cells leads to a rampant release of cytokines like IFN-γ, GM-CSF, TNF, IL-10, and IL-6, triggering an inflammatory response characterized by tachycardia, risk for acute respiratory distress syndrome (ARDS) acute hypoxic respiratory failure, and multiorgan failure." (PMID 34512641, 2021). "For example, TNF-α upregulates the expression of TF in acute respiratory distress syndrome (ARDS), and CRP drastically increases TF expression." (PMID 26667361, 2016). "Pulmonary infection is the most common cause of the acute respiratory distress syndrome (ARDS), that is associated with increased production and release of inflammatory cytokines/chemokines, such as tumor necrosis factor-α (TNF-α), interleukin-6 (IL-6), and IL-82." (PMID 27506372, 2016). "The concentration of TNFα used in our study is equivalent to the amount measured in bronchoalveolar fluid of human patients with acute respiratory distress syndrome, where TNFα concentration can reach ranges above 10 ng/mL." (PMID 28025644, 2016).
acute respiratory distress syndrome (continued). "In bronchoalveolar fluid of human patients with acute respiratory distress syndrome TNF-α concentrations can reach ranges above 10 ng/ml, but even higher local concentrations ranging from 0.6 to 2400 ng/ml have been found between intact cell structures." (PMID 24626175, 2014). "Kambas and coworkers suggest that TNFα is involved in the upregulation of TF in patients with acute respiratory distress syndrome." (PMID 23311309, 2013). "However, excessive TNF-α synergizes with IL-6 and IL-1β, leading to increased vascular permeability, pulmonary edema, and multi-organ damage, especially in acute respiratory distress syndrome (ARDS)." (PMID 41592028, 2026). "Similarly, TNF-α, a key effector in lung injury and acute respiratory distress syndrome (ARDS), exhibited a dramatic increase after 30 min, consistent with the role of electric field-induced oxidative stress in cytokine induction." (PMID 41155417, 2025). "This hyperinflammatory state is characterized by the overproduction of pro-inflammatory cytokines such as IL-6, TNF-α, and IL-1β, which can cause widespread tissue damage and contribute to the severe manifestations of COVID-19, such as acute respiratory distress syndrome (ARDS)." (PMID 40094929, 2025). "Through activation of NF-kappa-B, TNF-α suppresses the tight-junction protein claudin-5 that causes capillary leakage and massive influx of plasma proteins and white blood cells infiltrating the surrounding tissue and promotes the development of acute respiratory distress syndrome (ARDS)." (PMID 38256229, 2024). "Additionally, rosmarinic acid alleviated LPS-induced acute respiratory distress syndrome in mice, wherein it lowered the expression of TNF-α and IL-1β in the lung at protein level." (PMID 39129025, 2024). "They concluded that children with lowest serum concentrations of IL6 and TNFα, cytokines associated with acute respiratory distress syndrome (ARDS), recovered without sequelae." (PMID 35626859, 2022). "Furthermore, other research has also shown that lnc‐KCNQ1OT1 is able to negatively regulate IL‐6, TNF‐α, and IL‐10 expression in acute respiratory distress syndrome." (PMID 34761437, 2021). "One of the main causes of death from COVID-19 is acute respiratory distress syndrome (ARDS), and the main mechanism of ARDS is the “cytokine storm,” which is caused by immune effector cells releasing large amounts of pro-inflammatory cytokines (e.g., TNF-α, IFN-γ, IL-1β, IL-6, IL-12)." (PMID 33815131, 2021). "The excessive production of pro-inflammatory cytokines, such as TNF and IL-6, further induces endothelial damage and lung injury, and its more severe form, Acute Respiratory Distress Syndrome (ARDS), that can result in respiratory and/or multi-organ failure and death." (PMID 34576169, 2021). "In COVID-19 assessed by scRNA-seq, SARS-CoV-2 infection induced IL-1β and TNF-α production may promote mucin secretion from club cells, likely contributing to acute respiratory distress syndrome (ARDS)." (PMID 33106757, 2020). "Exuberant host responses, i.e., a cytokine storm with increase of macrophage-related cytokines, such as TNFα, IL-1β, and IL-6 can lead to life-threatening complications, such as acute respiratory distress syndrome (ARDS), which develops in approximately 20% of the patients." (PMID 32916949, 2020). "SARS-CoV2 induces an inflammatory storm in patients with severe symptoms, and multiple anti-inflammatory strategies are being tested for their ability to suppress virus-induced severe acute respiratory distress syndromes, including tocilizumab and anti-TNF-α therapy." (PMID 33196058, 2020). "TNF-α has been implicated in the pathogenesis of numerous inflammatory conditions including arthritis, asthma, chronic obstructive pulmonary disease (COPD), acute respiratory distress syndrome (ARDS), myocarditis and congestive heart failure." (PMID 31020451, 2019).
acute respiratory distress syndrome (continued). "IL-1 beta and TNF-alpha have been identified in bronchoalveolar lavage fluids from patients with acute respiratory distress syndrome (ARDS), an acute inflammatory process in the airspaces, and lung parenchyma that is not dissimilar to the lysis pneumopathy described in AML patients." (PMID 26124967, 2015). "Previous studies have demonstrated that highly elevated IL-6, IL-1, TNF-α, IFN-γ, MIP, CXCL10 are major causes of ARDS (acute respiratory distress syndrome) and mortality, and TGF-β1 could restrict inflammatory response." (PMID 25909459, 2015). "The clinical implication of this study stems primarily from the finding that protective ventilation affects the TNF-α levels of the hepatic efferent circulation, which have previously been correlated with hepatocellular dysfunction and severity of adult respiratory distress syndrome (ARDS)." (PMID 25958003, 2015). "TNF-alpha, and the cascade it induces, is known to attract neutrophils and other leukocytes in the lung and is thought to play an important role in the pathogenesis of acute respiratory distress syndrome and multiple organ dysfunction syndrome." (PMID 21731493, 2011). "This process triggers the excessive production of proinflammatory cytokines, including IL-6, IL-1β, and TNF-α, contributing to acute respiratory distress syndrome (ARDS), which is characterized by pulmonary edema, hypoxemia, and respiratory failure." (PMID 41521316, 2026). "A cytokine storm, characterized by excessive production of pro-inflammatory cytokines—particularly TNF-α, IL-6, and IL-1β—can trigger multiorgan damage and acute respiratory distress syndrome (ARDS)." (PMID 40807350, 2025). "The primary mediators of the cytokine storm, which contribute to acute respiratory distress syndrome (ARDS) and multiorgan damage, are interleukins (IL) 1, 6, and 17, as well as tumor necrosis factor alpha (TNF alpha)." (PMID 40431641, 2025). "The excessive production of IL-6, TNF, and IL-1β in glycolysis-driven immune cells results in widespread tissue damage, endothelial dysfunction, and acute respiratory distress syndrome (ARDS)." (PMID 40453076, 2025). "In studies of acute respiratory distress syndrome (ARDS), EVs carrying IL-4 and IL-10 payloads reduced inflammation by decreasing pro-inflammatory cytokines such as IL-1 beta and TNF alpha while increasing anti-inflammatory metabolites." (PMID 40428144, 2025). "In in vitro models of acute respiratory distress syndrome (ARDS), EVs-mediated MT from MSCs to human macrophages promotes phagocytosis and abolishes proinflammatory cytokine secretion [e.g., TNF-α] by macrophages, thereby mitigating lung injury." (PMID 38790026, 2024). "Excessive IL-6, IL-1β, and TNFα levels along with increased recruitment of immune cells in the airways contribute to epithelial damage and acute lung injury, driving the development of acute respiratory distress syndrome (ARDS), leading to severe vascular leakage and pulmonary edema." (PMID 35846766, 2022). "P1 could inhibit LPS-induced TNF-α expression and NF-kB activity in U937 cells and improve arterial oxygen pressure, oxygenation index, and lung pathology scores in rats with LPS-induced acute respiratory distress syndrome (ARDS)." (PMID 35955688, 2022). "This cytokine storm is characterized by elevated plasma concentrations of IL-2, IL-7, IL-10, GCSF, IP-10, MCP-1, MIP-1A and TNF-α, and contributes to the development of acute respiratory distress syndrome (ARDS)." (PMID 34208037, 2021). "Elevated early pro-inflammatory cytokines like interleukins (IL2, IL6, and IL10) and Tumor necrosis factor (TNF) in ICU subjects reflect the cytokine storm leading to acute respiratory distress syndrome (ARDS) and progressive multiple organ failure." (PMID 33869282, 2021).
acute respiratory distress syndrome (continued). "Numerous studies suggest that the curcuminoids inhibit proinflammatory cytokines such as IL-1, IL-6, IL-8, and TNF-α, prevent acute respiratory distress syndrome (ARDS), and repair the COVID-19-induced cellular damage." (PMID 34671412, 2021). "The proportion of LOX-1- or CD123-expressing ImNs is positively correlated with clinical severity, cytokine storm (IL-1β, IL-6, IL-8, TNFα), acute respiratory distress syndrome (ARDS), and thrombosis." (PMID 34616409, 2021). "Acute respiratory distress syndrome (ARDS) is the leading cause of death in COVID-19 patients, and DPP4 inhibitors may be a new treatment approach because they can decrease the production of inflammatory factors such as IL-1β, TNF-α, and IL-6." (PMID 34955820, 2021). "Inflammatory factors released during sepsis, such as tumor necrosis factor-α and interleukin-1β, disrupt the alveolar-capillary barrier, leading to pulmonary edema, respiratory failure, and progression to acute respiratory distress syndrome (ARDS)." (PMID 40313560, 2025). "The infection triggers the excessive production of pro-inflammatory cytokines (such as IL-6, TNF-a, IL-1, and CRP), thereby inducing acute respiratory distress syndrome." (PMID 40260091, 2025). "The primary complication of SARS-CoV-2 infection, Acute Respiratory Distress Syndrome (ARDS), stems from a ‘cytokine storm’ triggered by the uncontrolled release of proinflammatory cytokines and chemokines from immune cells, including IL-6, TNF-α, IFN-γ, and others." (PMID 39245237, 2025). "The second potential adverse outcome is hyperinflammation, characterized by high levels of C-reactive protein (CRP), interleukin (IL)-6, and tumor necrosis factor alpha (TNF-α), which can increase the risk of PLWH developing acute respiratory distress syndrome (ARDS)." (PMID 39597537, 2024). "A considerable proportion of individuals suffer from severe pneumonia, and some even develop acute respiratory distress syndrome (ARDS), which is believed to be triggered by cytokine storms (IL-6, IL-1, and TNF-α)." (PMID 37251406, 2023). "Case reports of inhibitors of TNF-a and IL-12p40 subunits causing interstitial pneumonia (IP) have been published in the literature, but no case of anti-IL-23p19 subunit biologics causing IP and acute respiratory distress syndrome (ARDS) has been reported before." (PMID 36891026, 2023). "IFN-γ and TNF-α overproduced by Th1 cells during response to SARS-CoV-2 elicit a mass death of virus-infected cells resulting in lung tissue damage and triggering acute respiratory distress syndrome." (PMID 37626620, 2023). "A suppression of NF-ĸB-dependent gene expression, including IL-1β, TNF-α, and VCAM-1, was also observed with olaparib in a mouse model of acute respiratory distress syndrome." (PMID 35740913, 2022). "NLRP3 inflammasome overactivation produces excessive IL-1β and downstream cytokines such as IL-6 and TNF-α, are also observed in acute respiratory distress syndrome (ARDS), ventilator induced lung injury (VILI), and disseminated intravascular coagulation (DIC)." (PMID 34150848, 2021). "TLR signaling pathways promote the production of IFN-α, IFN-β, IL-6, TNF, IFN-γ, CCL5, and IFN-stimulated genes, which are produced during acute respiratory distress syndrome (ARDS) and viral infections." (PMID 33953641, 2021). "IL-6 and TNF-α may be the key contributors to virus mediated respiratory diseases, including Acute Respiratory Distress syndrome (ARDS) and acute lung injury." (PMID 32269562, 2020). "The GSK3B inhibitor reduces the production of IL-6, TNFα, IL-17, and IL-1β in the BALF of mice with lipopolysaccharide-induced acute respiratory distress syndrome, thus relieving the lung injury." (PMID 31466385, 2019). "The elevated expression of TNF-α and IL-6 is an important step in the pathogenesis of ALI and acute respiratory distress syndrome." (PMID 29069220, 2017). "Acute respiratory distress syndrome (ARDS) is one disease mediated by TNF-α." (PMID 26990441, 2016).
acute respiratory distress syndrome (continued). "The lectin-like domain of TNF-α mimicked by an inhaled TIP peptide is a novel pharmacologic approach for treatment of edematous respiratory failure and acute respiratory distress syndrome (ARDS)." (PMID 24070340, 2013). "This recognition leads to the production of pro-inflammatory cytokines, including TNF, IL-6, IL-8, and IFN-α/β, resulting in symptoms such as fever, cough, rhinorrhea, sore throat, myalgia and, in severe cases, acute respiratory distress syndrome (ARDS) and pulmonary failure." (PMID 41012635, 2025). "Consistent with this dual role, mesenchymal stem cells have been shown to alleviate TNF-α- and LPS-induced apoptosis by activating the CXCL12/CXCR4 axis, thereby reducing lung injury and fibrosis in experimental acute respiratory distress syndrome (ARDS) models." (PMID 41614816, 2025). "Systemic inflammatory disorders such as Acute Respiratory Distress Syndrome (ARDS), vasculitis, sepsis, and acute cytokine release syndrome (CRS) induced by CAR-T therapies are associated with increased plasma levels of inflammatory stimuli such as cytokines TNFα and IFNγ." (PMID 40894883, 2025). "Massive systemic release of pro-inflammatory mediators such as interleukin (IL)-1β, IL-2, IL-6, IL-7, IL-10, tumor necrosis factor-α (TNFα), granulocyte colony-stimulating factor (G-CSF), etc., also known as cytokine storm, contributes to the acute respiratory distress syndrome (ARDS)." (PMID 35888733, 2022). "Therefore, it can prevent acute respiratory distress syndrome (ARDS) by decreasing the synthesis of pro-inflammatory Th1 cytokines, including tumor necrosis factor-alpha (TNF) and interferon, while simultaneously boosting anti-inflammatory cytokine expression by macrophages." (PMID 36295519, 2022). "Furthermore, in a model of LPS-induced Acute respiratory distress syndrome (ARDS), treatment with pyridostigmine reduced the number of macrophages and lymphocytes in bronchoalveolar lavage fluid and suppressed levels of TNFα, IL-1β, IL-6, and IFN-γ." (PMID 34948222, 2021). "Indeed, increased TNF-α, IL-1β, and IL-6 levels were detected in the BALF of patients with acute respiratory distress syndrome." (PMID 34745417, 2021). "4-OI was also found play an extremely important role in alleviating acute lung injury (ALI) or acute respiratory distress syndrome (ARDS) by inhibiting the expression of the downstream inflammatory cytokines (IL-β, IL-6, and TNF-α) and ROS to increase the activity of antioxidants in lung tissue." (PMID 34055739, 2021). "In an animal model of acute respiratory distress syndrome (ARDS), a syndrome with an increase in IL-6, TNF, and neutrophils in the lungs, NAR supplementation can reduce neutrophils infiltration and oxidative stress, greatly reducing airway inflammation and lung injury." (PMID 33101291, 2020). "Severe coronavirus disease 2019 (COVID-19) infection, particularly in those with acute respiratory distress syndrome (ARDS), is characterized by marked inflammation and immune activation with elevated levels of inflammatory cytokines, such as interleukin (IL)-6 and tumor necrosis factor." (PMID 33054818, 2020). "This exaggerated response leads to the production of a number of pro-inflammatory cytokines including IL-1β, IL-2, IL-6, IFN-γ, and TNF-α, which can lead to endothelial cell injury, acute lung injury (ALI), acute respiratory distress syndrome (ARDS), and vascular collapse (shock)." (PMID 24141285, 2013). "In this vein, during acute respiratory distress syndrome (ARDS), recruited alveolar neutrophils and Mos/macrophages acquire a classically activated phenotype (Mo1/M1) responsible for the release of several growth factors and proinflammatory cytokines, including CXCL1, CXCL2, CXCL10, CCL2, and TNF-α." (PMID 39940787, 2025). "Ang II plays a role in adaptive immunity during acute respiratory distress syndrome (ARDS) development by inducing proinflammatory IFN-γ, TNF-α, and IL-6 production." (PMID 35955801, 2022).